LTA4H (leukotriene A4 hydrolase)
Diseases named in the same sentence as LTA4H in open-access papers (continued):
Sharing a sentence is not in itself a finding about the gene and the disease.
atherosclerosis (3 papers, 2016 to 2024). A disease characterized by the build-up of fatty material and calcium deposition in the arterial wall resulting in partial or complete occlusion of the arterial lumen. "Genetic variations of key enzymes for LTB4 production, namely 5-LOX, 5-LOX activating protein (FLAP), and leukotriene A4 hydrolase (LTA4H), as well as alterations in their functionality are linked to atherosclerosis susceptibility and the prevalence of cardiovascular events." (PMID 30360467, 2018). "Certain B vitamins and vitamin A may be involved in inflammatory pathways associated with homocysteine and leukotriene A4 hydrolase (LTA4H), which have been considered independent predictors of low-grade inflammation, atherosclerosis process, and all-cause mortality." (PMID 38257081, 2024).
chronic obstructive pulmonary disease (3 papers, 2012 to 2020). A chronic and progressive lung disorder characterized by the loss of elasticity of the bronchial tree and the air sacs, destruction of the air sacs wall, thickening of the bronchial wall, and mucous accumulation in the bronchial tree. "For instance, in chronic obstructive pulmonary disease, the aminopeptidase activity of leukotriene A4 hydrolase (LTA4H) is inhibited, causing accumulation of proline-glycine-proline, which in turn, promotes neutrophil recruitment and chronic lung inflammation." (PMID 23227026, 2012). "It has been found that Lta4h is related to chronic obstructive pulmonary disease." (PMID 30770755, 2019).
lymph node metastasis (3 papers, 2018 to 2025). "The low expression of the proteins LTA4H, PGK1, NDRG1, COL6A1, and ITGAV in the saliva samples was associated with lymph node metastasis and advanced clinical staging (crosstabulation and chi-square test, P value < 0.05)." (PMID 30185791, 2018). "Interestingly, SRM-MS analysis showed CSTB, LTA4H, PGK1, COL6A1, ITGAV, and NDRG1 were significantly downregulated in patients with lymph node metastasis." (PMID 30185791, 2018). "In summary, a sensitive electrochemical biosensor was successfully developed to detect and quantify CSTB, LTA4H, and COL6A1 biomarkers in noninvasive saliva samples from OSCC patients, with and without lymph node metastasis." (PMID 40728373, 2025).
psoriasis (3 papers, 2018 to 2025). An autoimmune condition characterized by red, well-delineated plaques with silvery scales that are usually on the extensor surfaces and scalp. "Although known for its proinflammatory role in psoriasis, LTA4H levels were decreased in both sexes compared with controls." (PMID 40560578, 2025). "Given the elevated levels of leukotriene (LTB4) in psoriatic skin, the presence of a potential leukotriene A4 hydrolase inhibitor in the Nannochloropsis oceanica extract could represent a promising compound in the treatment of psoriasis." (PMID 39456489, 2024). "To ensure the human relevance, we examined the mRNA expressions of LTA4H, ALOX5, and LTB4R (a human LTB4 receptor) in human psoriasis lesions, using a public microarray data set23." (PMID 30089836, 2018).
pulmonary tuberculosis (3 papers, 2011 to 2023). A bacterial infection that affects the lungs and is caused by Mycobacterium tuberculosis. "If the anti-inflammatory role of LTA4H—through breaking down PGP—is more prominent in pulmonary TB compared with its role in TBM, this might explain our findings." (PMID 37520416, 2023).
uveal melanoma (3 papers, 2020 to 2024). A melanoma derived from melanocytes of the uveal tract. "LTA4H and FXR1 have been previously found to be over-expressed in both human and canine uveal melanomas and LTA4H has also been reported to be upregulated in feline ocular melanomas." (PMID 34966807, 2021). "Among them, an increased expression in Leukotriene A4 hydrolase (LTA4H) and Fragile X mental retardation-related protein 1 (FXR1) genes were related to metastasizing behavior in both human and canine uveal melanoma." (PMID 34966807, 2021). "Interestingly, expression profiling using a 12‐gene assay reliably distinguished metastasising from non‐metastasising uveal melanomas in humans and four of these genes (HTR2B, FXR1, LTA4H, and CDH1) are overexpressed in metastasising canine uveal melanoma." (PMID 32652526, 2020).
allergic contact dermatitis (2 papers, 2016 to 2021). An inflammatory skin condition caused by an immune response to direct contact between the skin and an allergen. "Next, we examined the effects of LTA4H deficiency on a mouse model of allergic contact dermatitis." (PMID 33037399, 2021). "Thus, the unexpected inhibition of the aminopeptidase activity of LTA4H provides a novel insight into the mechanism of allergic contact dermatitis caused by bufexamac." (PMID 27126280, 2016). "By generating LTB4-producing enzyme LTA4H knockout mice and CD11c promoter-driven Cre recombinase-expressing BLT1 conditional knockout (BLT1 cKO) mice, we showed that the migration of BLT1hi DCs exacerbated allergic contact dermatitis." (PMID 33037399, 2021).
chronic lung disease (2 papers, 2015 to 2017). According to the definitions of the American and British Thoracic Societies, including pulmonary functional tests, X-rays, and CT scans for items such as fibrosis, bronchiectasis, bullae, emphysema, nodular or lymphomatous abnormalities. "We have previously demonstrated that the enzyme LTA4H is able to potently degrade the neutrophil chemoattractant PGP to ensure the efficient resolution of inflammation and that this system is perturbed in chronic lung diseases, enabling PGP accumulation and persistent neutrophilia." (PMID 29202450, 2017).
coronary artery disease (2 papers, 2009 to 2017). "Genetic variants in the key enzyme involved in the leukotriene pathway, the leukotriene A4 hydrolase (LTA4H) gene, have been related to depression in subjects with coronary artery disease." (PMID 27555379, 2017).
COVID-19 (2 papers, 2022 to 2023). A disease caused by infection with severe acute respiratory syndrome coronavirus 2. "We found that the plasma levels of HP, LTA4H, S100A9, SAA1, SAA2, and SERPINA3 were significantly elevated in more severe COVID-19 conditions, exhibiting good clinical predictive value and promising applications." (PMID 37197655, 2023).
depression (2 papers, 2017 to 2025). "Following the analysis of the metabolic pathways, seven genes including ALOX5, LTA4H, CYP4Y, PLA2G2C, AKR1C1, AKR1D1 and CYP17A1 were employed to elucidate further the potential mechanisms underlying CS treatment of depression." (PMID 40370520, 2025).
extrapulmonary tuberculosis (2 papers, 2019 to 2023). A tuberculosis that occurs at body sites other than the lung. "In a Chinese population study, LTA4H gene polymorphism was also reported to be associated with extrapulmonary tuberculosis." (PMID 31093505, 2019). "Recent studies have shown that the polymorphism locus in the promoter region of LTA4H gene affects LTB4 expression level and the susceptibility to extrapulmonary tuberculosis." (PMID 31093505, 2019).
laryngeal squamous cell carcinoma (2 papers, 2020 to 2023). A squamous cell carcinoma that arises from the larynx. "Recent research shows that the increased expression of LTA4H in laryngeal squamous cell carcinoma (LSCC) promotes tumor proliferation, migration, and metastasis." (PMID 36923505, 2023). "Therefore, the potential function of LTA4H in laryngeal squamous cell carcinoma deserves further study." (PMID 36923505, 2023). "In order to explore the relationship between LTA4H and laryngeal squamous cell carcinoma (LSCC), or more broadly head and neck squamous cell carcinoma (HNSCC), we first studied the expression level of LTA4H in LSCC tissues and normal tissues through The Cancer Genome Atlas (TCGA) database." (PMID 36923505, 2023). "In laryngeal squamous cell carcinoma (LSCC) tissues, AIMP1 and leukotriene A4 hydrolase (LTA4H) were upregulated and promoted the proliferation, migration, and invasion of LSCC cells." (PMID 32709848, 2020).
lung carcinoma (2 papers, 2023 to 2025). "As an essential hydrolase for LTB4 production (Vo, Jang & Jeong, 2018), upregulated LTA4H has been found to be linked with various malignancies, such as colon, esophageal, and lung cancer." (PMID 36923505, 2023). "Leukotriene A4 hydrolase (LTA4H) plays an important role in cancer development and its presence in upregulating key cancer pathophysiology in certain type of cancers such as thyroid cancer, esophageal and lung cancer have been studied." (PMID 40433427, 2025).
multiple myeloma (2 papers, 2021 to 2023). "This compound, considered a pro-drug activated by aminopeptidases expressed in multiple myelomas (such as APN, leucyl aminopeptidase 3 (LAP3), arginyl aminopeptidase (RNPEP), and leukotriene A4 hydrolase (LTA4H)) has been studied in phase I/II (HORIZON, ANCHOR) and phase III (OCEAN) trials." (PMID 36979703, 2023). "Melflufen could be hydrolyzed to its active form by the aminopeptidases LAP3, LTA4H, RNPEP, and ANPEP, all of which are expressed in multiple myeloma." (PMID 33810334, 2021).
pulmonary arterial hypertension (2 papers, 2024 to 2025). Pulmonary arterial hypertension (PAH) is a group of diseases characterized by mean pulmonary artery pressure >20 mmHg and elevated pulmonary arterial resistance leading to right heart failure. "In contrast to 5-LO and COX2, a downstream leukotriene metabolizing enzyme LTA4H had significant associations with the decline in DLCO, a parameter that depends not solely on lung structure and volume, but which is also influenced by lung perfusion and pulmonary hypertension." (PMID 39199199, 2024).
sarcoidosis (2 papers, 2020 to 2023). Sarcoidosis is a multisystemic disorder of unknown cause characterized by the formation of immune granulomas in involved organs. "According to Gini score calculated from gene expression values, we examined the top-6 most important AA metabolism-related genes (including PLA2G6, PLA2G7, AKR1C1, AKR1C3, LTA4H, and PTGER4) in sarcoidosis, whose expression showed a positive correlation with sarcoidosis samples." (PMID 33097805, 2020).
T-cell lymphoma (2 papers, 2015 to 2016). "The most significantly mutated genes in Gr T-cell lymphomas are PSMA1, the cytochrome C oxidase subunit COX8A, and leukotriene A4 hydrolase (LTA4H)." (PMID 26377837, 2015). "Looking at the most significantly mutated genes in B-cell and T-cell lymphomas across the three studied breeds, genes not previously implicated in human lymphoma include well-known cancer-associated genes such as LTA4H and PSMA1, indicating potential treatment with proteasome inhibitors." (PMID 26377837, 2015). "rs2660852 flanked 5′UTR of LTA4H (leukotriene A4 hydrolase), rs477145 was intronic to TIAM1 (T-cell lymphoma invasion and metastases) and rs2835931 was intronic to KCNJ6 (potassium channel, inwardly rectifying subfamily J, member 6)." (PMID 26959888, 2016). "The proximal protein coding genes included LTA4H (leukotriene A4 hydrolase) on chromosome 12, TIAM1 (T-cell lymphoma invasion and metastases) and KCNJ6 (potassium channel, inwardly rectifying subfamily J, member 6) both on chromosome 21." (PMID 26959888, 2016). "LTA4H and PSMA1 have not been associated with human T-cell lymphoma, but have been associated with other human cancers and indicate new treatment options for Gr T-cell lymphoma." (PMID 26377837, 2015).
viral infection (2 papers, 2022). "Along with these proteins, several other viral infection induced proteins such as LGALS3BP, GOLM1, and LTA4H were also increased." (PMID 35958562, 2022).
Allergy (1 paper, 2020). An allergy is an immune response or reaction to substances that are usually not harmful. "Based on their association with allergy and the protein fold change (more than 1.1 or less than 0.9) between ATI responders and non-responders, four potential genes (MUC5B, LBP, C4BPB, LTA4H) were identified as potential biomarkers that indicate an effective AIT." (PMID 33329520, 2020).
bacteremia (1 paper, 2024). "Among the top differentially expressed genes in young infants with UTI without bacteremia, only two genes directly annotated to immune response were upregulated, i.e., leukotriene A4 hydrolase (LTA4H) and CD44 molecule." (PMID 38732074, 2024).
bacterial meningitis (1 paper, 2015). Inflammation of the membranes surrounding the brain and spinal cord due to a bacterial infection. "Since the inflammatory network regulated by LTA4H may be fundamental to the host inflammatory response to diverse infections, we hypothesized that outcome of dexamethasone treatment in bacterial meningitis is dependent on LTA4H genotype." (PMID 25799317, 2015).
Burkitt lymphoma (1 paper, 2018). A rare form of malignant mature B-cell non-Hodgkin lymphoma. "Use of Bestatin, a well-known LTA4H inhibitor or LTA4H silencing induced proliferation arrest in KSHV+ PEL cells when compared to non-infected (KSHV–; BJAB) Burkitt’s lymphoma cells." (PMID 30159133, 2018).
cardiomyopathy (1 paper, 2021). A disease of the heart muscle or myocardium proper. "Several of the proteins impacted by myectomy (POSTN, MMP12, CDON, NAMPT, HAMP, LTA4H) were previously reported to be altered in cardiovascular disease, cardiomyopathy, or vascular disease with effects mediated through inflammatory mechanisms." (PMID 33804404, 2021).
cholestasis (1 paper, 2020). Impairment of the bile flow caused by obstruction within the liver, or outside the liver in the bile duct system. "Additionally, by acting on LTA4H, a key target that triggers inflammatory responses, PF inhibits the inflammatory response caused by cholestasis and damages liver cells." (PMID 33192530, 2020).
contact dermatitis (1 paper, 2016). An inflammatory skin condition caused by direct contact between the skin and either an irritating substance or an allergen. "Indiscriminately targeting LTA4H dual enzyme activities may account for the observed paradoxical effect of bufexamac on the treatment of contact dermatitis, although the potential effect of bufexamac on the LTB4 level and Pro–Gly–Pro degradation in patients warrant further clinical investigation." (PMID 27126280, 2016).
diabetes (1 paper, 2022). "Crude odds ratio estimates remained within the range of 1.5–2.0 and 2.0–2.5 range for LTA4H and HGF, respectively, when stratifying for time to death from first symptom onset, time-to-event, ECG classification, chronic coronary syndrome medication, and diabetes status." (PMID 36142157, 2022).
emphysema (1 paper, 2024). "In addition, Haemophilus influenzae, a key player in COPD airway microbiota, was found to be genetically and transcriptionally associated with LTA4H encoding leukotriene A4 hydrolase that can be converted to neutrophil attractant leukotriene B4 in promoting emphysema." (PMID 38622589, 2024).
glioma (1 paper, 2023). A benign or malignant brain and spinal cord tumor that arises from glial cells (astrocytes, oligodendrocytes, ependymal cells). "Therefore, the elevated expression of LTA4H/LTA4H and LTC4S/LTC4S can be considered as specific to GBM and glioma, respectively." (PMID 36765904, 2023).
laryngeal carcinoma (1 paper, 2023). Carcinoma that arises from the laryngeal epithelium. "However, more study is necessary to fully understand the specific molecular mechanism of LTA4H in laryngeal carcinoma." (PMID 36923505, 2023). "In addition, we plan to conduct functional studies of LTA4H in the future, such as comparing laryngeal cancer cells with cells that overexpress LTA4H/LTA4H knockdown, to validate the findings from the RIP-seq analyses." (PMID 36923505, 2023). "The low expression of LTA4H in laryngeal cancer tissues was consistent with previous studies." (PMID 36923505, 2023).
melanoma (1 paper, 2021). A malignant, usually aggressive tumor composed of atypical, neoplastic melanocytes. "Thirty-two melanomas were LTA4H-positive (32/32), with a percentage of positive neoplastic cells of 31–50% in 2 cases, 51–70% in five and above 70% in 25 cases." (PMID 34966807, 2021). "Thirty-two (32/32) melanomas immunolabelled for LTA4H and 33/34 for FXR1." (PMID 34966807, 2021).
metastatic tumors (1 paper, 2015). "The gene encoding leukotriene A4 hydrolase (LTA4H) appears down-regulated in high metastatic risk tumors; we detected this gene product in only one of eight metastatic tumors." (PMID 26305875, 2015).
mycobacterial infection (1 paper, 2020). "The profiles of immune response proteins relevant for mycobacterial infection showed that LTA4H and cathepsin L1 levels increased in response to vaccination or vaccination and infection." (PMID 32344637, 2020).
ocular melanoma (1 paper, 2021). A melanoma that arises from the structures of the eye or ocular adnexa. "LTA4H was also specifically demonstrated to be overexpressed in human, canine and feline ocular melanomas." (PMID 34966807, 2021).
ovarian carcinoma (1 paper, 2024). A malignant neoplasm originating from the surface ovarian epithelium. "The article highlights the significant role of LTA4H in influencing tumor characteristics and the immune microenvironment in the context of ovarian cancer." (PMID 38764576, 2024). "Knockdown of LTA4H has been shown to inhibit the proliferation of ovarian cancer cells, while high expression of LTA4H leads to a decrease in infiltrating CD8+ T cells, which are crucial for anti-tumor immune responses." (PMID 38764576, 2024). "Targeting LTA4H, whether through genetic manipulation or chemical inhibition, can yield favorable therapeutic effects for ovarian cancer." (PMID 38764576, 2024). "Positive correlation between LTA4H and poor prognosis in ovarian cancer has been observed, with the lack of LTA4H enhancing sensitivity to Cisplatin." (PMID 38764576, 2024).
pancreatic cancer (1 paper, 2017). "Within a xenograft mouse model, resveratrol delayed or suppressed the promotion of pancreatic cancer via inhibiting the activity of leukotriene A4 hydrolase (LTA4H), which stimulates the generation of pro-inflammatory cytokines and mediators, and also stimulates cancer cell proliferation." (PMID 29194365, 2017).
parasitic diseases (1 paper, 2018). "These cattle are known to be tolerant to different endemic parasitic diseases, and so the immunity-related genes within the candidate regions identified (e.g. LTA4H, IL7, IL15, FCN, LTA4H and NFAM1) are potential targets of natural selection." (PMID 30114214, 2018).
periodontal disease (1 paper, 2018). "For example, leukotriene A4 hydrolase is typically involved in alleviating inflammation; thus, downregulation of this gene could lead to the promotion of an inflammatory state typical of periodontal disease." (PMID 29666288, 2018).
skin cancer (1 paper, 2018). "Another recent study has indicated that LTA4H regulates the cell cycle and the knockout of the protein reduced skin cancer development in mouse model." (PMID 30185791, 2018).